DGAT2 (diacylglycerol O-acyltransferase 2)
Diseases named in the same sentence as DGAT2 in open-access papers (continued):
Sharing a sentence is not in itself a finding about the gene and the disease.
cancer (22 papers, 2015 to 2025). A tumor composed of atypical neoplastic, often pleomorphic cells that invade other tissues. "High DGAT2 expression is associated with prolonged overall survival in cancer patients, and these findings have been validated via in vitro and in vivo experiments, indicating that DGAT2 overexpression can inhibit cell proliferation and reduce tumor growth." (PMID 38376693, 2024). "Here the authors show that active IRE1α cleaves DGAT2 mRNA encoding the rate-limiting enzyme in the synthesis of triacylglycerols, suggesting a role of IRE1α in reprogramming lipid metabolism in cancer cells." (PMID 35524156, 2022). "Scd, Scd2, Dgat2, Fads2, Lpin1, Gpat3, Acaa2, Lpcat3, Pcyt2 and Pla2g4a have been reported to be closely associated with cancer." (PMID 35122680, 2022). "Taken together, these data suggest that the role of deregulated DGAT2 is context-dependent across cancers and is associated with structural alterations in conserved functional domains." (PMID 34439946, 2021). "In this report we characterized DGAT2, a gene required for triacylglycerol synthesis and cell membrane structure using the Catalogue of Somatic Mutations in Cancers (COSMIC)." (PMID 34439946, 2021). "This suggests that DGAT2 mutations and alterations in cancer cells are specific to drive cellular transformation and immortalization." (PMID 34439946, 2021). "Analyzing the mutational landscape of more regulators such as DGAT2 increases our understanding of deregulated lipid metabolism in cancer." (PMID 34439946, 2021). "Using data from the Catalogue of Somatic Mutations in Cancer (COSMIC), we analyzed all cancer genetic DGAT2 alterations, including mutations, copy number variations and gene expression." (PMID 34439946, 2021). "In this study, we carried out a pan-cancer analysis of DGAT2 mutations." (PMID 34439946, 2021). "Our analysis identified several things about mutated DGAT2 in cancer tissues." (PMID 34439946, 2021). "Cancer cells exhibit altered lipid metabolism and mutations in DGAT2 may contribute to this state." (PMID 34439946, 2021). "Correlation analyses revealed a positive correlation between DGAT1 and DGAT2 mRNA levels in cancer cell lines (Spearman r = 0.813, p < 0.017), suggesting potential coordinated regulation between these isoforms at the transcriptional level." (PMID 41041279, 2025). "Existing research consistently highlights the overexpression of DGAT1 and DGAT2 in various cancers, including prostate, breast, and OCs." (PMID 41041279, 2025). "DGAT1 and DGAT2 are promising targets in cancer treatment, playing critical roles in LD formation and tumor progression, highlighting their potential for developing new therapeutic strategies." (PMID 41041279, 2025). "Inhibition of TAG synthesis by targeting DGAT1 and DGAT2 with specific small inhibitors effectively depleted the formation of LDs and had differential effects on cell growth depending on the type of FA in cancer cells." (PMID 38786008, 2024). "A controversial association between the prognosis of cancer patients and the expression levels of DGAT1 and DGAT2 in different types of tumors has been reported." (PMID 38500157, 2024). "It is still unclear why DGAT1 and DGAT2 behave differently in various cell types and which transcription factor regulates their expression in cancer cells." (PMID 36009491, 2022). "Using data from the Catalogue of Somatic Mutations in Cancers (COSMIC), we analyzed the mutational landscape of DGAT2 and characterized pathogenic mutations associated with changes in DGAT2 function that likely contribute to cellular transformation." (PMID 34439946, 2021). "On the contrary, inhibition of DGAT1 and DGAT2 disrupts TG fatty acid composition and compromises in vivo cancer growth by increasing apoptosis and reducing proliferation of cancer cells." (PMID 31315616, 2019). "DGAT2 protein levels were significantly higher than DGAT1 in the same cancer cell lines." (PMID 41041279, 2025).
cancer (continued). "Furthermore, we demonstrated that IRE1α inhibition sensitized cancer cells to starvation through increased DGAT2 activity." (PMID 35524156, 2022). "Furthermore, many publications have shown that DGAT1 is a better target than DGAT2 for cancer therapy." (PMID 36009491, 2022). "Compound libraries targeting obesity as well as cancer should be evaluated in a system that could mimic human and mouse DGAT2 structure and activity with ease and high throughput screening capacity." (PMID 36479627, 2022). "Furthermore, we evaluated the expression of Diacylglycerol Acyltransferases (DGAT) 1 and 2 which participate in TAG synthesis, and found an increase in DGAT1 and DGAT2 expression in Elovl5-silenced cancer cells." (PMID 36056008, 2022). "Second, DGAT2 mutations are found in all cancer types suggesting that deregulated gene activity is not cancer specific." (PMID 34439946, 2021). "Likewise, DGAT1 and DGAT2 are frequently overexpressed in many cancers while being unchanged in the murine liver tumors." (PMID 34629057, 2021). "This work uncovers unknown functions of DGAT2 in cancers and suggests that its role may be more complex than previously appreciated." (PMID 34439946, 2021). "Using the criteria of circadian proteomic expression, circadian expression in multiple tissues and independent gene knockdown data, we propose six genes (Por, Mtss1, Dgat2, Pim3, Ppp1r3b, Upp2) involved in metabolism and cancer for further experimental investigation." (PMID 26576534, 2015). "DGAT2 mutations in cancers are common but have not yet been thoroughly investigated." (PMID 34439946, 2021). "From these genes, we identified DGAT2 as a RIDD substrate and uncovered the importance of DGAT2-mediated regulation of TAG metabolism in TNBC, thus linking IRE1α activity to TAG biosynthesis in cancer cells." (PMID 35524156, 2022). "Since DGAT1 and DGAT2 are enzymes that catalyze the last step in TAG synthesis and control the biogenesis of LDs, inhibition of their functions results in an increased concentration of free FAs and other lipid species in the cytoplasm, ultimately leading to higher “lipotoxicity” for cancer cells." (PMID 38786008, 2024). "Of note, in 6.5/cancer cells, DGAT2 inhibition failed to inhibit invasion." (PMID 31974393, 2020). "DGAT2 deserves as much attention as DGAT1, if not more, in cancer research." (PMID 36439875, 2022). "We also documented a significant upregulation of DGAT1 mRNA and protein expression in pH 6.5-adapted cancer cells that was completely prevented upon TGF-β2 silencing or TGF-βRI blockade; DGAT2 expression was not altered in response to Trabedersen or SB431542." (PMID 31974393, 2020).
tumor (17 papers, 2014 to 2026). "DGATs and PLINs are pivotal in LD metabolism and tumor progression in OC, with DGAT2 being a good candidate as prognostic and diagnostic marker." (PMID 41041279, 2025). "Diagnostic assessments using ROC analysis revealed that elevated DGAT2 levels detected in tumor tissue, PF, and plasma exhibited robust diagnostic capabilities." (PMID 41041279, 2025). "DGAT2 encodes a key enzyme that catalyzes the synthesis of triglycerides and has been reported to be involved in the reprogramming of lipid metabolism in tumor cells, driving tumor progression." (PMID 36761027, 2023). "In control mice, Ppar and associated target genes Fas and Dgat2 peaked during the light cycle, while in the tumor-bearing cachectic animals rhythmicity was lost and mRNA levels were markedly decreased at most time points." (PMID 24667661, 2014). "Moreover, significant Spearman correlations between DGAT2 expression in tumor tissue and plasma, and between PF and plasma, indicate that plasma DGAT2 reliably reflects tumor‐associated expression." (PMID 41041279, 2025). "The six‐gene diagnostic model (AIFM2, ABCG1, LIPG, DGAT2, LPCAT1, and VCP) demonstrated near‐perfect classification of tumor versus normal tissues (AUC ≈0.99 in ROC analysis; 99.8% accuracy in SVM analysis)." (PMID 40804485, 2025). "Several inhibitors of DGAT1 and DGAT2 have been created over the past decade, showing anti-tumor effects in pre-clinical models of tumors and metabolic improvements in clinical trials." (PMID 38500157, 2024). "By reprogramming the activities of DGAT1 and DGAT2, tumor cells can form more LDs to tolerate their enhanced free FA metabolism and prevent possible lipotoxicity and cell death." (PMID 38500157, 2024). "Overexpression of DGAT2 in the tumor tissues predicted longer survival in patients with HCC (70% vs 50%, p = 0.02) after nearly five years of follow-up." (PMID 38500157, 2024). "Furthermore, a significant association was found between elevated levels of DGAT1, DGAT2, PLIN2, PLIN3, and TG and malignancy, especially in advanced tumor stages, underscoring their promise as therapeutic targets in OC." (PMID 41041279, 2025). "Within tumor tissue, TG levels exhibited a positive correlation with DGAT1 at both the mRNA (r = 0.630, p = 0.008) and protein levels (r = 0.562, p = 0.026), while demonstrating a significant positive association with DGAT2 protein (r = 0.850, p = 0.003)." (PMID 41041279, 2025). "Notably, we found significant correlations between DGAT1 and DGAT2 mRNA expression and the tumor aggressiveness marker Ki67." (PMID 41041279, 2025). "Notably, different roles of DGAT1 and DGAT2 in tumor growth and prognosis have been reported in different types of tumors, increasing the difficulty of applications of DGATs in the clinical setting." (PMID 38500157, 2024). "The reason why high expression of DGAT2 appears to inhibit tumor growth in HCC remains unclear." (PMID 38500157, 2024). "Heatmap analysis showed marked upregulation of PLIN3, whereas LIPG, DGAT2, CIDEC, and PLIN1 were down-regulated in tumor tissues and GbPDTOs compared to those in normal tissues." (PMID 41376821, 2025). "After BALB/c nude mice were injected with DGAT2-overexpressing HCC cells for 28 days, the tumor weight and volume were markedly decreased compared with the control group." (PMID 38500157, 2024). "The phenomenon we observed was different from the findings of previous reports that tumor cells rely solely on DGAT1 rather than DGAT2 to regulate TG synthesis and LD formation." (PMID 41214328, 2025). "Additionally, DGAT1 and DGAT2 play crucial roles in tumor dynamics by modulating epithelial‐mesenchymal transition (EMT), influencing both tumor invasion and metastasis." (PMID 41041279, 2025). "However, the protein levels of DGAT2 are reduced in HCC, and overexpression of DGAT2 inhibits cell proliferation and colony formation in vitro and tumor formation in vivo." (PMID 33413672, 2021).
tumor (continued). "One possible explanation is that FA metabolism is extremely active in hepatocytes, and the increased DGAT2 activity with lower free FAs and higher TG synthesis may not be favorable to tumor growth in HCC." (PMID 38500157, 2024). "Increased DGAT2 activity was detected in gastric tumor cell lines when co-cultured with adipocytes, which subsequently upregulated the FAO pathway and production of NADPH and decreased intracellular ROS, thereby promoting the resistance of tumor cells to anoikis." (PMID 38500157, 2024). "We found that DGAT1 is overexpressed in tumor tissues from GBM patients and genetic or pharmacological inhibition of DGAT1, but not DGAT2, suppresses LD/TAG formation and reduces GBM tumor growth." (PMID 36009491, 2022). "Interestingly, the increased protein levels in tumor tissues compared with nonmalignant tissues was more pronounced for DGAT1 than for DGAT2, despite DGAT2′s higher baseline levels." (PMID 41041279, 2025).
infection (10 papers, 2017 to 2025). The state of being infected such as from the introduction of a foreign agent such as serum, vaccine, antigenic substance or organism. "In contrast, DGAT1 and DGAT2 mRNA levels remained relatively stable, with DGAT2 mRNA levels significantly decreasing at 48 hours post infection." (PMID 41306517, 2025). "Surprisingly, the overexpression of DGAT2 strongly reduced reporter gene expression with a 13-fold reduction in the first and a 100-fold reduction in the second round of infection as compared to the control." (PMID 39241103, 2024). "After verifying the antiviral activity of the HA-tagged DGAT2 construct, the system allowed us to study the antiviral effect of DGAT2 when induced at different times prior to and post infection." (PMID 39241103, 2024). "A GO functional classification of the DEGs obtained after infection with sh-DGAT2 revealed enrichment in three categories: biological processes, cellular compounds, and molecular functions." (PMID 35883393, 2022). "Compared to sh-NC, sh-DGAT2 infection of BSCs significantly inhibited the mRNA expression of PAX7, MYOD1, MYOG, and MYR4 (p < 0.05)." (PMID 35883393, 2022). "Since Dgat2 and Plin have been both observed at the surface of cytosolic M. marinum, the dynamics of both proteins during infection was monitored in infected Dictyostelium expressing RFP-Plin and Dgat2-GFP." (PMID 28103313, 2017). "At late infection stages (45 hpi), Dgat2-GFP surrounded bacteria that had fully escaped from the MCV to the cytosol (yellow arrow)." (PMID 28103313, 2017). "When the localization of both Dgat proteins was monitored during infection, we observed that many of the Dgat2-GFP-positive LDs clustered around the MCV." (PMID 28103313, 2017). "At 3 and 6 h after infection, ZIKV RNA levels were comparable in all groups; compared with the control group, ZIKV RNA levels in DGAT2KD cells were decreased by ~7-fold at 12 h after infection, especially by ~9-fold at 24 h after infection, indicating that DGAT2 acts at the viral replication step." (PMID 39449854, 2024). "Interestingly, in this study, DGAT1 and DGAT2 knockdown in human colonic Caco-2 cells and lung Calu-3 cells led to significantly reduced viral yields following infection compared to control-transfected cells." (PMID 37113005, 2023). "Besides, PPARγ, some of the critical enzymes involved in fatty acid biosynthesis, TAG biosynthesis, cholesterol esterification like Fasn, Dgat1, Dgat2, Mgat1, Acat1, Acat2, etc., showed a temporal increase in expression levels at the later time points post-infection." (PMID 41358489, 2025). "In Dictyostelium cells overexpressing Dgat2-GFP, we also observed ILI accumulation in the few bacteria that escaped to the cytosol early in infection." (PMID 28103313, 2017). "Moreover, complete labelling of the bacteria by Dgat2-GFP never occurred in infections with ΔRD1 mutant bacteria." (PMID 28103313, 2017). "In this context, it is interesting that the intracellular growth of M. marinum as measured by bacterial luciferase activity was not different in wild type cells and Dgat1- or Dgat2-GFP overexpressors, even when fed with FA prior to infection." (PMID 28103313, 2017).
metabolic disease (6 papers, 2019 to 2024). A congenital disorder (due to inherited enzyme abnormality) or acquired (due to failure of a metabolically important organ) disorder resulting from an abnormal metabolic process. "Overall, our findings have underscored the relevance of TRF in preserving heart health under circadian disruptions and provided potential targets, such as Dgat2, and strategies for therapeutic interventions in mitigating cardiac aging, metabolic disorders, and cardiac diseases in humans." (PMID 38616316, 2024). "Therefore, we assessed DGAT2 protein expression in microsomes isolated from sural nerve biopsies of diabetic patients with PN who were stratified based on severity of metabolic disease (higher HbA1c or TG and cholesterol levels)." (PMID 31822493, 2020).
peripheral neuropathy (2 papers, 2021 to 2023). A disorder affecting the peripheral nervous system. "Lipidomic and transcriptomic analyses of nerve tissue biopsies from hyperlipidaemic diabetic patients with peripheral neuropathy revealed an increase in the expression of the diacylglycerol acyltransferase 2 (DGAT2) enzyme, which mediates the committed step in TG synthesis." (PMID 38139843, 2023).
DGAT2 also shares sentences with these, for which no sentence is quoted: pancreatic cancer (4 papers); Hyperglycemia (2); cardiac arrhythmia (1); cardiac diseases (1); cervical cancer (1); colitis (1); colorectal cancer (1); COVID-19 (1); energy metabolism disorders (1); Hypocholesterolemia (1); Impaired glucose tolerance (1); ischemic stroke (1); liver (1); liver cancer (1); myopathy (1); ovarian carcinoma (1); ovarian tumor (1); prostate tumor (1); sarcopenia (1); uveal melanoma (1).